DPP4 (dipeptidyl peptidase 4)
Diseases named in the same sentence as DPP4 in open-access papers (continued):
Sharing a sentence is not in itself a finding about the gene and the disease.
heart failure (continued). "The plasma DPP4 activity was correlated negatively with cardiac function in heart failure patients." (PMID 24416433, 2014). "EXAMINE, a trial evaluating the DPP-4 inhibitor alogliptin in patients with recent acute coronary syndrome, observed a neutral effect on cardiovascular outcomes, though the results suggested a non-significant trend toward increased heart failure risk." (PMID 39768866, 2024). "This distinction provided valuable information, indicating that not all DPP-4 inhibitors might carry the same heart failure risk and underscoring the importance of evaluating cardiovascular effects on a drug-by-drug basis within the same class." (PMID 39768866, 2024). "Additionally, beyond GLP-1, DPP-4 also acts on other substrates that may influence immune responses and fibrotic processes in the myocardium, adding complexity to its role in heart failure." (PMID 39768866, 2024). "Personalized Medicine: Exploring the role of genetic factors in predicting response to DPP-4 inhibitors could lead to more personalized treatment approaches in heart failure patients, allowing for individualized selection of antidiabetic agents based on genetic predispositions." (PMID 39768866, 2024). "The HRs for DPP-4 inhibitors vs. metformin were 1.01 (95% CI: 0.84–1.20) for major cardiovascular events, 0.89 (95% CI: 0.68–1.16) for myocardial infarction, 1.11 (95% CI: 0.94–1.31) for heart failure, 1.12 (95% CI: 0.89–1.40) for a stroke, and 1.06 (95% CI: 0.93–1.21) for all cardiovascular events." (PMID 36078917, 2022). "Some studies indicated that specific DPP4-inhibitors may lead to adverse cardiovascular events, such as recurrent myocardial infarction and hospitalization, due to heart failure in selected populations, while the others take a positive attitude among cardiovascular outcome in patients with ESRD." (PMID 33172034, 2020). "Moreover, DPP‐4 inhibitors might alleviate the COVID‐19 related cardiovascular injury including arrhythmia, acute coronary syndrome and heart failure." (PMID 32713161, 2020). "Thus, we aimed to evaluate whether the heart failure protective effect of SGLT-2i differs depending on the underlying CVD and the prescription period compared with dipeptidyl peptidase-4 inhibitors (DPP-4i)." (PMID 29935543, 2018). "Recent meta-analyses including the finished major and many smaller cardiovascular safety studies for DPP-4 inhibitors have different conclusions, ranging from no increased risk for the hospitalization of heart failure after DPP4 inhibitor use to an increased risk." (PMID 28894748, 2017). "However, additional references suggest that certain risks like heart failure and related hospitalisation, and pancreatitis, may be increased with the use of DPP-4 inhibitors compared to other anti-diabetic treatments, independently of age group." (PMID 29047372, 2017). "It has been shown that DPP-4 inhibitor-treated type 2 diabetic patients had lower risks for cardiovascular disease as compared to those for non-DPP-4 inhibitor users, except metformin users, and its use did not increase the risk of heart failure compared with sulfonylurea." (PMID 29195509, 2017). "Similarly, a recent pre-specified patient-level pooled analysis of available trials of LGT did not report an association between the DPP-4 inhibitor and increased CV risk (including heart failure)." (PMID 27391040, 2016). "Since in some but not in all studies DPP-4 inhibitors were associated with an increased the risk for heart failure, these compounds may also not be used in patients with concomitant occurrence of CVD and heart failure." (PMID 27071968, 2016). "Moreover, DPP4 inhibitors or protease-resistant SDF1α analogs might become novel therapies in pathologies such as ischemic heart disease and heart failure." (PMID 26544044, 2015). "On the other hand, compared to DPP-4 inhibitors and sulphonylureas, SGLT-2 inhibitors showed more advantages in preventing hospital admissions for heart failure and ≥40% decline in eGFR." (PMID 40574081, 2025).
heart failure (continued). "The rates of admission to hospital for heart failure were lower for SGLT-2 inhibitors compared with sulfonylureas (0.46, 0.20 to 1.05) and with DPP-4 inhibitors (0.32, 0.12 to 0.85)." (PMID 38719492, 2024). "DPP-4 inhibitor administration has yielded mixed results in treating patients with CAD and heart failure in both pre-clinical and clinical studies, with many clinical studies showing no significant change in cardiovascular mortality or related complications." (PMID 39074126, 2024). "We provide here the first evidence that the protein expression of DPP4 and NPY decreased in cardiac tissue samples of heart failure patients." (PMID 35884882, 2022). "Additionally, a clinical trial showed that hypoglycemic agents, such as GLP-1R agonists and DPP-4 inhibitors, could not reduce the risk of heart failure." (PMID 35360240, 2022). "Here, we showed that the protein expression of DPP4 and NPY decreased in the cardiac tissue of heart failure patients." (PMID 35884882, 2022). "Other medication classes, including DPP-4 inhibitors; insulin (glargine); alpha-glucosidase inhibitors; glinides; D2-dopamine agonists; GLP-1 agonist; and sulfonylurea are neutral to heart failure outcomes." (PMID 34926000, 2021). "NPs play central roles in regulation of heart failure (HF), and are inactivated through not only NP receptor-C, but also neutral endopeptidase (NEP), dipeptidyl peptidase-4 and insulin degrading enzyme." (PMID 29344085, 2018). "Currently, results for hospitalization for heart failure in the DPP-4 inhibitor trials are homogenous, highlighting potential differences between DPP-4 inhibitors within the same drug class." (PMID 30343339, 2018). "Interestingly, DPP4 may itself be implicit in the mechanism of heart failure." (PMID 29040423, 2018). "Preferred drugs in heart failure include metformin (NYHA Stage I-II), acarbose and GLP-1 analogs/DPP-4 inhibitors, although the evidence base to recommend the latter is weak." (PMID 23841986, 2013). "This examination sought to methodically examine cardiovascular sequelae, notably heart failure, among users of dipeptidyl peptidase 4 (DPP-4) inhibitors when compared with nonusers." (PMID 40832578, 2025). "Interestingly, it has been found that DPP‐4 inhibitors also exhibit protective effects against metabolic CVD,18, 19 but their role in heart failure remains controversial." (PMID 39968759, 2025). "Combination Therapies: Examining the combination of DPP-4 inhibitors with other cardioprotective agents, such as SGLT2 inhibitors, could reveal synergistic effects in heart failure patients." (PMID 39768866, 2024). "However, the trend towards a slight increase in heart failure events, though not statistically significant, has highlighted the importance of carefully monitoring patients with a history of heart failure or those at high risk of heart failure when prescribing DPP-4 inhibitors." (PMID 39768866, 2024). "By inhibiting DPP-4, DPP-4 inhibitors prolong the activity of GLP-1, enhancing its cardioprotective properties, which could theoretically benefit patients with heart failure." (PMID 39768866, 2024). "Furthermore, the neutral effect on heart failure hospitalizations in TECOS helped distinguish sitagliptin from saxagliptin and underscored the need for individualized consideration of DPP-4 inhibitors based on each drug’s cardiovascular profile." (PMID 39768866, 2024). "Most of DPP4 inhibitors (DPP4i) have been investigated in in vivo and in vitro models of diabetic and nondiabetic cardiovascular diseases including heart failure, hypertension, myocardial ischemia or infarction, atherosclerosis, and stroke." (PMID 35945358, 2022). "This decrease in DPP4 expression was not related to the etiology of heart failure (ischemic or non-ischemic origin)." (PMID 35884882, 2022). "Cardiac expression of DPP4 and NPY decreased in heart failure patients." (PMID 35884882, 2022).
heart failure (continued). "Clinical outcomes with DPP-4 inhibitors showed no or partially negative effects on heart failure hospitalization, despite data from animal models and several smaller studies that have suggested potential beneficial effects of these agents." (PMID 34205870, 2021). "Pooled analysis of currently available Cardiovascular Outcome Trials (CVOTs) of glucose-lowering medications reported that dipeptidyl peptidase-4 inhibitor (DPP-4i) and GLP1-RA resulted in a neutral effect on heart failure hospitalization in patients with T2DM." (PMID 32754118, 2020). "While DPP-4 inhibitors appear to worsen rates of hospitalization in those with heart failure, they had no additional adverse effects on other CV outcomes." (PMID 32010059, 2019). "As a result, it seems to be not a class effect of DPP-4 inhibitors in the view of increasing heart failure." (PMID 29301579, 2018). "Circulating levels of SDF-1 and the expression of receptors for SDF-1 are already increased in patients with heart failure, in the absence of DPP-4 inhibition." (PMID 29310647, 2018). "Small-scale studies showed that dipeptidyl peptidase (DPP)-4 inhibitors and thiazolidinediones (TZD) were effective in improving left ventricular diastolic function, but larger clinical studies showed exacerbation of heart failure with the use of such agents." (PMID 29788955, 2018). "As VSMCs are involved in the pathogenesis of cerebro-cardiovascular diseases, we speculated that the protective effect of DPP-4 inhibitors against atherosclerosis, AMI, heart failure may be through interaction with VSMCs." (PMID 29100378, 2017). "Despite the results of animal studies suggesting that DPP-4 inhibitors are promising candidates for treatment of heart failure, human studies have not shown a beneficial effect so far." (PMID 28771625, 2017). "A recent study showed that the risk for heart failure is particularly high in the presence of CKD, thus patients with CVD, CKD and heart failure should be treated with SGLT2 inhibitors but not with DPP-4 inhibitors." (PMID 27071968, 2016). "So, it is still not possible to rule out the existence of an interaction between DPP4 inhibition and heart failure." (PMID 26146634, 2015). "Also, patients with heart failure had increased circulating levels of DPP-4 and there was an inverse correlation between serum DPP-4 activity and left ventricular ejection fraction." (PMID 25285158, 2014). "The present analysis showed that treatment with DPP-4 inhibitors did not significantly increase cardiovascular outcomes and heart failure in these patients with T2DM, indicating that these drugs may be safe to use in terms of cardiovascular events." (PMID 40832578, 2025). "Among the ten most frequent side effects of DPP4 inhibitors are gastrointestinal nonspecific inflammation, hypersensitivity, acute pancreatitis, haemodynamic oedema, malignancies, angioedema, embolic/thrombotic events, hepatic disorders, and cardiac failure." (PMID 39861115, 2025). "Other DPP-4 inhibitors, such as sitagliptin, have shown a neutral cardiovascular profile in separate studies like TECOS, suggesting that the heart failure risk may not be a class effect but rather specific to saxagliptin or certain patient populations." (PMID 39768866, 2024). "SGLT2 inhibitor users had a lower prevalence of chronic kidney disease, heart failure, and a history of stroke, and they were more likely to have used insulin, metformin, and glucagon-like peptide-1 (GLP1) agonists in the baseline period when compared to DPP4 inhibitor users." (PMID 38846094, 2024). "In addition, long-term clinical outcome studies using different DPP-4 inhibitors revealed that development of adverse clinical events including heart failure and cardiovascular death did not increase with chronic DPP-4 inhibition." (PMID 33401457, 2021).
heart failure (continued). "Whereas in human clinical studies DPP‐4 inhibition does not prevent heart failure hospitalizations, it remains unknown whether it may prevent the development of early diastolic dysfunction and the progression towards HFpEF." (PMID 33295687, 2021). "Before PSSWs, there were more female, rural resident, hospitalization history of heart failure, use of angiotensin-converting enzyme inhibitors (ACEi) or angiotensin II receptor blockers (ARBs), and use of other oral hypoglycemic agent (OHA) in the pioglitazone group than the DPP4-inhibitor group." (PMID 33172034, 2020). "However, it remains puzzling why clinical trials for DPP-4 inhibitors like saxagliptin failed to improve the cardiovascular outcome or even increased the rate of hospitalization for heart failure." (PMID 31341533, 2019). "As a result, our result showing that linagliptin had a neutral effect on hospitalization for heart failure could be more convincing and supported that it should not be a class effect of all DPP-4 inhibitors in regards to heart failure." (PMID 29301579, 2018). "It remains to be determined whether this reflects a class effect of DPP-4 inhibitors, as a numerical (but non-significant) increase in hospitalization for heart failure was also seen in the EXAMINE study of alogliptin but not in the TECOS study of sitagliptin." (PMID 29540217, 2018). "Indeed, some preclinical studies suggest that inhibition of DPP-4 by different gliptins results in less cardiac dysfunction in a murine model of HFD-induced fibrosis and inflammation and in a rat model of heart failure by inhibiting NF-κB and by reducing the formation of pro-inflammatory cytokines." (PMID 30619349, 2018). "Based on the three trials currently available, it seems the excessive heart failure effect may not be a class effect of DPP4 inhibitors." (PMID 28619058, 2017). "DPP4 activity in serum was not altered in the heart failure population." (PMID 26544044, 2015). "Importantly, TECOS was methodologically rigorous in adjudicating heart failure outcomes, and the absence of a signal for HHF helped clarify that the risk may not represent a uniform class effect across all DPP-4 inhibitors." (PMID 41246652, 2025). "While the SAVOR-TIMI-53 clinical trial showed increased heart failure hospitalizations, this finding has not been redemonstrated in other clinical studies, and a recent study from Japan showed better long-term outcomes in heart failure patients treated with DPP-4 inhibitors." (PMID 39074126, 2024). "Moreover, some classes of glucose-lowering drugs, such as DPP-4 inhibitors, sodium-glucose cotransporter-2 inhibitors (SGLT2i), and GLP1 agonists, have demonstrated significant benefits in reducing major adverse cardiovascular events, heart failure hospitalization, and the progression of CKD." (PMID 34946320, 2021). "In addition to atherosclerosis, DPP‐4 also plays a negative role in the process of heart failure." (PMID 32713161, 2020). "Interestingly, reduction in fat mass and increase in TBW would keep the weight of the subjects neutral as seen in most trials with DPP4 inhibitors, however this may not be clinically relevant in subjects with no overt heart failure." (PMID 29724198, 2018). "However, it is noteworthy that no prior studies directly compared DPP4 inhibitors with SGLT2 inhibitors, and our finding that at a class level DPP4 inhibitors are associated with higher risk of heart failure hospitalization than SGLT2 inhibitors will be an important addition to the literature." (PMID 28756774, 2017). "In this study, we hypothesized that SGLT2 inhibitors elicit more cardioprotective effects than DPP-4 inhibitors, specifically in patients with early-stage T2DM and without CVD (including not having heart failure)." (PMID 33530982, 2021).
heart failure (continued). "Further studies on a larger number of subjects are needed to assess whether longer-term DPP-4 inhibitor treatment is safe and has beneficial effect on cardiac function in T2DM patients with or without overt heart failure." (PMID 28490337, 2017). "In addition, a meta-analysis of 70 trials of DPP-4 inhibitors enrolling 41,959 patients reported a reduction in MACE (n = 495 total events of CV death, nonfatal MI, and stroke and acute coronary syndromes and/or heart failure; odds ratio, 0.71 [95% CI, 0.59, 0.86])." (PMID 24490835, 2014).
colorectal cancer (122 papers, 2000 to 2026). A primary or metastatic malignant neoplasm that affects the colon or rectum. "Analysis of colorectal cancer and lung cancer patients showed a similar trend toward beneficial effects associated with DPP4 inhibition; however, further studies are required on the clinical impact of DPP4 inhibition on tumor patients." (PMID 33796097, 2021). "CD26 (dipeptidyl peptidase-4) is a marker of colorectal cancer stem cells with high metastatic potential and resistance to therapy." (PMID 40806753, 2025). "For example, DPP4 upregulation can facilitate distant metastasis of esophageal adenocarcinoma and colorectal cancer." (PMID 38890707, 2024). "Yet, a recent study stated that DPP-4 inhibitors considerably worsen the results for colorectal cancer patients who have undergone curative surgery." (PMID 39390508, 2024). "Cysteine dioxygenase 1 (CDO1) modulates erastin in vitro in gastric cancer cells, whereas cisplatin and dipeptidyl peptidase-4 (DPP4) regulate erastin-induced ferroptosis in colorectal cancer." (PMID 38528461, 2024). "Subsequently, relevant research has reported elsewhere that the DPP-4 inhibitor lessens the disease-free survival in patients with T2DM after curative resection for colorectal cancer." (PMID 37760498, 2023).